CTSLP8 (cathepsin L pseudogene 8)
Synonyms: formerly CTSL1P8
Gene: Transcribed unprocessed pseudogene on chromosome 9 (87,844,154 to 87,847,314, forward strand). Ensembl gene ENSG00000234575.
Diseases named in the same sentence as CTSLP8 in open-access papers:
CTSLP8 is named in the same sentence as 8 diseases in open-access papers, as found by Europe PMC text mining. Sharing a sentence is not in itself a finding about the gene and the disease. The quoted sentences say what the papers report.
ovarian carcinoma (6 papers, 2021 to 2026). A malignant neoplasm originating from the surface ovarian epithelium. "Analysis of tissue samples showed that increased expression of CTSLP8 was linked to the development of cisplatin resistance and poor clinical outcomes in ovarian cancer patients." (PMID 41362671, 2026). "The study discovered that CTSLP8 promoted the growth of ovarian cancer cells and heightened their resistance to cisplatin." (PMID 41362671, 2026). "We previously demonstrated that the pseudogene CTSLP8 can regulate the expression of CTSL1 in ovarian cancer through a ceRNA mechanism." (PMID 34510316, 2022). "Pseudogene CTSLP8, acting as a sponge for miR-199a-5p, promotes ovarian cancer metastasis formation." (PMID 36348434, 2022). "Ectopic expression of lnc-CTSLP8 enhanced the proliferation, migration, and invasion of ovarian cancer cells, but these effects were abrogated by Z-FY-DMK." (PMID 33933142, 2021). "Further, public database analysis also revealed lnc-CTSLP8 upregulation in advanced-stage or high-grade ovarian cancer patients." (PMID 33933142, 2021). "lnc-CTSLP8 acts as a ceRNA in ovarian cancer and represents a potential therapeutic target for metastatic ovarian cancer." (PMID 33933142, 2021). "Through overexpression/knockout of lnc-CTSLP8 in ovarian cancer cells in vitro and in vivo, we established lnc-CTSLP8 as a potent oncogene, which acts by enhancing the autophagy and EMT in ovarian cancer cells." (PMID 33933142, 2021). "Further, lnc-CTSLP8 expression in ovarian cancer peritoneal metastasis tissues (n = 22) was even higher than that in ovarian cancer in situ tumor tissues." (PMID 33933142, 2021). "Mechanistically, lnc-CTSLP8 contributed to the progression of ovarian cancer by acting as a ceRNA to its cognate gene, CTSL1." (PMID 33933142, 2021). "When overexpressed, lnc-CTSLP8 promoted ovarian cancer in vitro and in vivo by acting as a sponge for miR-199a-5p." (PMID 33933142, 2021). "The expression of lnc-CTSLP8 in ovarian cancer was analyzed in public databases (TCGA and GEO) and validated via qRT-PCR." (PMID 33933142, 2021). "We then established lnc-CTSLP8 overexpression and knockout cell lines to investigate the role of lnc-CTSLP8 in ovarian cancer cells in vitro and in vivo." (PMID 33933142, 2021). "Meanwhile, ectopic expression of lnc-CTSLP8 significantly altered the LC3-II/LC3-I ratio in ovarian cancer cells." (PMID 33933142, 2021). "A novel pseudogene, lnc-CTSLP8, was identified in ovarian cancer, with significantly elevated expression in metastatic tumor tissues compared to primary ovarian tumors." (PMID 33933142, 2021). "Next, we inhibited CTSL1 activity in lnc-CTSLP8-overexpressing ovarian cancer cells using Z-FY-DMK, a selective CTSL1 inhibitor." (PMID 33933142, 2021). "To validate the function of lnc-CTSLP8 in vivo, we established an orthotopic ovarian cancer mouse model." (PMID 33933142, 2021). "However, research on the relationship between CTSLP8 expression and resistance to the chemotherapy drug cisplatin in ovarian cancer remains limited." (PMID 41362671, 2026). "Moreover, the expressions of CTSLP8 among some tumors were also analyzed, which showed the specificity of CTSLP8 in ovarian cancer." (PMID 34510316, 2022). "GSEA suggested that the EMT was promoted in ovarian cancer cells after lnc-CTSLP8 overexpression." (PMID 33933142, 2021). "Further, lnc-CTSLP8 overexpression upregulated N-cadherin, indicating that lnc-CTSLP8 might promote ovarian cancer autophagy and EMT in vivo." (PMID 33933142, 2021). "GSEA suggested that autophagy was enhanced in ovarian cancer cells under lnc-CTSLP8 overexpression." (PMID 33933142, 2021). "Autophagy and EMT in ovarian cancer were also enhanced by lnc-CTSLP8." (PMID 33933142, 2021). "We observed these autophagy defects in lnc-CTSLP8 knockout ovarian cancer cells." (PMID 33933142, 2021).
ovarian carcinoma (continued). "TEM revealed greater numbers of enlarged autophagosomes (AU), autolysosomes (AL), and dysfunctional mitochondria (MT) following lnc-CTSLP8 knockout, whereas overexpression decreased the number of autolysosomes and dysfunctional mitochondria in ovarian cancer cells." (PMID 33933142, 2021). "Consequently, CTSLP8 could represent a potential therapeutic target for ovarian cancer." (PMID 41362671, 2026). "Thereafter, lnc-CTSLP8 was overexpressed in ovarian cancer cell lines with relatively low lnc-CTSLP8 expression (SKOV3 and OVCA420) and knocked out in the ovarian cancer cell line with the highest lnc-CTSLP8 expression (Hey)." (PMID 33933142, 2021). "In this study, we screened RNA expression patterns in metastatic ovarian cancer tissues via RNA sequencing and identified non-coding CTSL pseudogene 8 (lnc-CTSLP8), which was significantly upregulated." (PMID 33933142, 2021). "Furthermore, lncRNA CTSLP8 (cathepsin L pseudogene 8) stimulates c-Myc expression by forming a transcription complex with PKM2, which enhances glycolysis and DDP resistance in ovarian cancer." (PMID 40264038, 2025).
breast carcinoma (3 papers, 2020 to 2022). "Previous studies have reported that the pseudogene CTSLP8 is upregulated in breast cancer and that the upregulated CTSLP8 is an indicator of poor prognosis in breast cancer." (PMID 34510316, 2022). "We find that increased CTSLP8 (Wald p-value = 5.0 × 10− 05), increased EEF1GP4 (Wald p-value = 1.0 × 10− 06), decreased HLA-K (Wald p-value = 8.0 × 10− 05), increased CBX1P3 (Wald p-value = 1.0 × 10− 03), and increased RPS10P20 (Wald p-value = 2.0 × 10− 03) indicate worse prognosis in breast cancer." (PMID 32241256, 2020).
cervical squamous cell carcinoma (1 paper, 2022). A squamous cell carcinoma arising from the cervical epithelium. "And the upregulated expression of CTSLP8 was associated with poor prognosis in patients with OC, and similar trends were observed in other tumors, such as cervical squamous cell carcinoma and endocervical adenocarcinoma (CESC), but the p values were not statistically significant." (PMID 34510316, 2022).
ovarian tumor (1 paper, 2021). "The overexpression/knockout of lnc-CTSLP8 in mouse orthotopic ovarian tumor tissues was confirmed via immunofluorescence using the lnc-CTSLP8 probe." (PMID 33933142, 2021). "In contrast, we observed suppressed autophagy and EMT in the ovarian tumor tissues of Hey-CTSLP8-KO mice." (PMID 33933142, 2021).
tumor (3 papers, 2021 to 2025). "The in vivo effect of CTSLP8 overexpression and knockdown on the chemotherapy response of tumors was examined using a mouse subcutaneous tumor model." (PMID 34510316, 2022). "Immunofluorescence analysis revealed that the expression of c-Myc was upregulated in the tumor tissues exhibiting enhanced CTSLP8 expression." (PMID 34510316, 2022). "The dataset analysis demonstrated that CTSLP8 was upregulated in chemotherapy-resistant tumor tissues." (PMID 34510316, 2022). "SKOV3-CTSLP8-OE-inoculated mice developed more metastases, while less metastases were observed in Hey-CTSLP8-KO mouse tumor models." (PMID 33933142, 2021). "CTSLP8 was upregulated in the chemotherapy-resistant tumor tissues." (PMID 34510316, 2022). "Similarly, lnc-CTSLP8 overexpression enhanced tumor formation and tumor weight in vivo, yet these effects were also suppressed in mice treated with Z-FY-DMK." (PMID 33933142, 2021). "Moreover, lnc-CTSLP8 overexpression led to reduced overall survival in tumor-bearing mice, whereas mice with Hey-CTSLP8-KO tumors had longer overall survival than their Hey-CTSLP8-NC and Hey-CTSLP8-WT counterparts." (PMID 33933142, 2021). "Additionally, tumor growth was rapid in the CTSLP8-high expression group." (PMID 34510316, 2022). "In OC, HMGA1P6, CTSLP8, and SDHAP1 are known to competitively bind to their paralogs, influencing tumour metastasis and paclitaxel resistance." (PMID 40000433, 2025). "The tumor chips were subjected to FISH and IHC analyses to examine the expression patterns of CTSLP8, PKM2, and c-Myc." (PMID 34510316, 2022).
cancer (1 paper, 2021). A tumor composed of atypical neoplastic, often pleomorphic cells that invade other tissues. "In particular, the enhancement of autophagy and EMT observed in lnc-CTSLP8 OE cancer cells was reversed by treatment with a selective CTSL1 inhibitor, indicating that the function of lnc-CTSLP8 depended on CTSL1 activity." (PMID 33933142, 2021).
CTSLP8 also shares sentences with these, for which no sentence is quoted: endocervical adenocarcinoma (1 paper); metastatic tumor (1).